FBLN1 (fibulin 1)
Diseases named in the same sentence as FBLN1 in open-access papers (continued):
Sharing a sentence is not in itself a finding about the gene and the disease.
osteosarcoma (2 papers, 2023 to 2024). A usually aggressive malignant bone-forming mesenchymal neoplasm, predominantly affecting adolescents and young adults. "This unexpected observation may be in part due to the presence of a fibroblastic osteosarcoma tumor in our dataset and the broad expression of fibroblast markers (FAP, FBLN1) across all tumor cell clusters." (PMID 37609233, 2023).
peripheral arterial disease (2 papers, 2020 to 2022). A disorder of the arteries supplying the upper and lower extremity and the visceral organs. "A study of the relationship between FBLN1 and the arterial wall indicated that the level of serum FBLN1 was statistically related to the aortic augmentation index of peripheral arterial disease." (PMID 32430056, 2020).
scleroderma (2 papers, 2022 to 2025). Scleroderma is a rare autoimmune connective tissue disorder characterized by abnormal hardening of the skin and, sometimes, other organs. "Besides, α‐smooth muscle actin (αSMA), Fibulin 1 (FBN1), and vimentin (VIM) which are often used to identify pathologic fibroblasts and myofibroblasts were highly expressed in the dermis of scleroderma skin, compared to the control group." (PMID 35315234, 2022).
airway hyperresponsiveness (1 paper, 2010). "A murine model of airway hyperresponsiveness (AHR) was used to explore the biological significance of fibulin-1." (PMID 20967215, 2010).
aortic regurgitation (1 paper, 2014). "However, the link between fibulin-1 and NT-proBNP in our study was unrelated to aortic regurgitation and LV ejection fraction, but linked closely with the AVAI." (PMID 25014213, 2014). "Fibulin-1 was unrelated to aortic regurgitation, left ventricular mass, and ejection fraction." (PMID 25014213, 2014).
astrocytoma (1 paper, 2019). "Fibulin-1 (FBLN1) was described as being up-regulated in high-grade astrocytoma, and Fibulin-2 (FBLN2) and Fibulin-5 (FBLN5) was described as being down-regulated in grade II/III/IV compared with grade I astrocytoma." (PMID 31357616, 2019).
atrial fibrillation (1 paper, 2013). A disorder characterized by an electrocardiographic finding of a supraventricular arrhythmia characterized by the replacement of consistent P waves by rapid oscillations or fibrillatory waves that vary in size, shape and timing and are accompanied by an irregular ventricular response. "On the other hand, a down-regulation of fibulin-1 has been described in atrial fibrillation." (PMID 23294625, 2013).
babesiosis (1 paper, 2023). Babesiosis refers to a condition caused by microscopic parasites that infect the red blood cells. "Given its increase in abundance with increase of severity of babesiosis, fibulin-1 could be a potential biomarker for monitoring the disease." (PMID 37353646, 2023).
bladder tumor (1 paper, 2014). "Immunohistochemistry results revealed that blood vessel quantification reduced drastically in the 5637 tumors over-expressing fibulin-1 (P < 0.05), which indicated that fibulin-1 significantly inhibit bladder tumor angiogenesis." (PMID 25234557, 2014).
cardiac ischemia (1 paper, 2014). "A study on rats found that levels of fibulin-1 are down-regulated in events related to cardiac ischemia." (PMID 25014213, 2014).
cervical cancer (1 paper, 2021). A primary or metastatic malignant neoplasm involving the cervix. "The nature expression of ANT3, FBLN1 in vitro were investigated by qPCR and western blotting in the wide type cervical cancer cell lines, SiHa (HPV16+), Hela (HPV18+), Caski (HPV16+, HPV18+), C-33A (HPV−) as well as H8 (Immortalized ceivical epithelial cells)." (PMID 33602229, 2021). "After the loss of E6/E7 by using CRISPR/Cas9 gene editing, the content of ANT3 and FBLN1 in KoE6/E7 SiHa were downregulated, which indicated the expression of ANT3 and FBLN1 in cervical cancer may be affected by HPV infection." (PMID 33602229, 2021). "We verified FBLN1 and ANT3 as promising early indicators of HPV-associated cervical carcinoma." (PMID 33602229, 2021). "However after the loss of E6/E7, the content of ANT3 and FBLN1 in KoE6/E7 SiHa were downregulated compared to wide type SiHa by qPCR and immunofluorescence, which indicated the expression of ANT3 and FBLN1 in cervical cancer may be affected by HPV infection." (PMID 33602229, 2021). "Our study suggests that FBLN1 and ANT3 can be used as general serum protein markers for cervical carcinoma and HPV infection thus warranting the future development of ELISA kits for the detection of FBLN1 (IIEVEEEQEDPYLNDR) and ANT3 (VAEGTQVLELPFK) peptides." (PMID 33602229, 2021). "We identified two proteins (FBLN1 and ANT3), which were closely related to cervical precancerous lesions and cervical carcinoma." (PMID 33602229, 2021). "In the current study, ELISA and PRM-MS were applied to demonstrate that the expression of FBLN1 and ANT3 increase in cervical carcinoma and precancerous lesion groups, in close relationship with HPV status and the carcinogenic protein E6/E7, showing co-occurrences of 75.7 % and 85 %, respectively." (PMID 33602229, 2021).
chronic hepatitis B (1 paper, 2020). "In our research, the serum Fibulin-1 levels were significantly increased in HCC patients than in healthy controls, chronic hepatitis B patients and individuals with HBV-induced liver cirrhosis." (PMID 32612994, 2020). "Moreover, the serum Fibulin-1 levels were significantly elevated in HCC patients than in healthy controls, chronic hepatitis B patients and HBV-induced liver cirrhosis patients." (PMID 32612994, 2020). "Importantly, the circulating cell-free RNA (cfRNA) level of Fibulin-1 in the serum were significantly increased in patients with HCC compared with those in healthy controls, individuals with chronic hepatitis B and patients with HBV-induced liver cirrhosis." (PMID 32612994, 2020).
colorectal adenoma (1 paper, 2011). An adenoma that arises from the colon or rectum. "CXCL1 expression is up-regulated in colorectal adenomas and adenocarcinoma, inhibiting apoptosis and inversely linked to expression of fibulin-1, an extra-cellular matrix protein implicated in control of tumour cell migration." (PMID 21249124, 2011).
cryptorchidism (1 paper, 2021). The failure of one or both testes of a male fetus to descend from the abdomen into the scrotum during the late part of pregnancy. "FBLN1 gene point mutation is associated with FBLN1-related developmental delay-central nervous system anomaly-syndactyly syndrome which is characterized by delayed motor development, intellectual disability, dysarthria, pseudobulbar signs, cryptorchidism, and syndactyly." (PMID 33687501, 2021).
diabetic angiopathy (1 paper, 2020). "In general, the indication of FBLN1 can be used as a prognostic marker of the risk of cardiovascular disorders, which is important for patients with T1DM and T2DM since they are at a high risk of diabetic angiopathy." (PMID 33184417, 2020).
diabetic retinopathy (1 paper, 2016). "Whereas no specific role for Fbln1 has been described so far in the retina, Fibulin2 (Fbln2) has been implicated in retinal detachment observed in diabetic retinopathy, retinopathy of prematurity and other retinal complications." (PMID 26918849, 2016).
dilated cardiomyopathy (1 paper, 2024). Cardiomyopathy which is characterized by dilation and contractile dysfunction of the left and right ventricles. "Enrichment analysis revealed that FBLN1 is primarily associated with focal adhesion, aldosterone synthesis and secretion, thyroid hormone synthesis, dilated cardiomyopathy, and adrenergic signaling in cardiomyocytes, as shown in the GO analysis." (PMID 39201719, 2024).
ductal carcinoma in situ (1 paper, 2003). "Examination of ductal carcinoma in situ and invasive breast carcinomas revealed that tumour cells expressed fibulin-1 protein, with the connective tissue surrounding these tumour cells also exhibiting moderate expression of fibulin-1." (PMID 12644824, 2003).
Granuloma (1 paper, 2025). A compact, organized collection of mature mononuclear phagocytes, which may be but is not necessarily accompanied by accessory features such as necrosis. "Fibroblasts within Mtb granulomas displayed elevated expression of pro-inflammatory genes, recapitulating the broader inflammatory signature, and showed increased levels of tissue remodeling genes COL1A1 and FBLN1." (PMID 41586350, 2025).
Hypoglycemia (1 paper, 2016). A decreased concentration of glucose in the blood. "Both FBLN-1 and VSC proteins were also increase in mice undergoing hypoglycemia." (PMID 26918849, 2016).
hypospadias (1 paper, 2024). Hypospadias is the displacement of the urethral meatus on the ventrum of the penis. "Proteins such as fibulin-1, elastin, matrix metalloproteinase-1, basic fibroblast growth factor, and α-smooth muscle actin play roles in hypospadias development." (PMID 39476852, 2024). "The study’s aim is to investigate the differences in messenger RNA (mRNA) expression of fibulin-1, elastin, matrix metalloproteinase-1, basic fibroblast growth factor, and α-smooth muscle actin between the ventral and dorsal tunica dartos in patients with hypospadias and chordee." (PMID 39476852, 2024). "The proteins fibulin-1, elastin, matrix metalloproteinase-1 (MMP-1), basic fibroblast growth factor (bFGF or FGF-2), and α-smooth muscle actin (α-SMA) play roles in hypospadias development." (PMID 39476852, 2024). "Therefore, this protocol is designed to investigate the differences in mRNA expression of fibulin-1, elastin, MMP-1, bFGF, and α-SMA between the ventral and dorsal tunica dartos in patients with hypospadias and chordee." (PMID 39476852, 2024).
IgG4-related Disease (1 paper, 2021). "We identify the LCN2 gene being over-expressed in IPF, CF, Schistosomiasis and SSc and the FBLN1 gene being under-expressed in CF, Myelofibrosis, Polycystic Kidney Disease and SSc and over-expressed in IgG4-related Disease." (PMID 33826640, 2021). "This fact can partially justify the under-expression of FBLN1 in 4 diseases of our transcriptomics analyses (even though it was over-expressed in IgG4-related Disease), since gene expression is measured by the level of the corresponding mRNA present in a cell." (PMID 33826640, 2021).
infantile epilepsy (1 paper, 2025). "At the protein level, western blots validated expression changes in CBS (mental retardation), NEAS/SPTAN1 (associated with infantile epilepsy), FBLN1 (cardiac morphogenesis), FXR1 (muscle development), and SHANK2 (neuronal differentiation in the retina)." (PMID 39508990, 2025).
keloid (1 paper, 2022). An irregularly shaped, elevated mark on the skin caused by deposits of excessive amounts of collagen during wound healing. "The fact that we observed the upregulation of FBLN1, FN1, and PDGFRL in keloids in our proteomic profiles enhances the possibility of this hypothesis." (PMID 35435317, 2022).
leukemia (1 paper, 2024). A malignant (clonal) hematologic disorder, involving hematopoietic stem cells and characterized by the presence of primitive or atypical myeloid or lymphoid cells in the bone marrow and the blood. "In addition, out of two infant and two adult MLLr leukemia cell lines assayed in the presence of Fn1 and/or Fbln1, only the infant MLL::ENL ALL cell line KOPN-8 showed a decrease in viability, which was attributed to Fn1." (PMID 38555405, 2024). "We found both Vcam1 and, as previously highlighted, Fn1 and its antagonist Fbln1, to be higher abundant in FLEF relative to BMEF, suggesting a stronger impact of VLA-4/Vcam1 and VLA-4/Fn1 interactions in fetal-origin leukemia." (PMID 38555405, 2024).
liver cancer (1 paper, 2020). An epithelial or non-epithelial malignant neoplasm that arises from the liver. "Fibulin-1 silencing significantly increased apoptosis in liver cancer cell lines upon nutrient starvation by downregulating Mcl-1 and Bcl-xL expression." (PMID 32612994, 2020). "Thus, Mcl-1 and Bcl-xL are the predominant mediators of Fibulin-1 siRNA-induced apoptosis in liver cancer cells, although other unidentified targets may also be involved." (PMID 32612994, 2020).
lymph node metastasis (1 paper, 2015). "Our data indicated that there was no statistically remarkable correlation between sex, age, histological differentiation, lymph node metastasis, grade, and FBLN1 hypermethylation." (PMID 25837757, 2015).
macular degeneration (1 paper, 2016). Loss of vision in the central portion of the retina (macula), secondary to retinal degeneration. "In eight sporadic cases, we detected eight heterozygous rare sequence variants in six macular degeneration genes (CFH; FBLN1, OMIM 135820; FBLN3/EFEMP1, OMIM 601548; FBLN5, OMIM 604580; HMCN1, OMIM 608548; FBN2, OMIM 612570)." (PMID 27007659, 2016).
malaria (1 paper, 2014). Malaria is a serious and sometimes fatal disease caused by a parasite that commonly infects a certain type of mosquito which feeds on humans. "The set of proteins that was denoted ‘Malaria decreased’ contained fibulin-1 (FBLN1) and RANTES (CCL5), both involved in endothelial cell death, whilst glutathione peroxidase (GPX1) protects from oxidative stress." (PMID 24743550, 2014).
meningioma (1 paper, 2020). A generally slow growing tumor attached to the dura mater. "Hence, reduced FBLN1 expression in grade III vs. grade I meningiomas detected in this study supports the notion that loss of this protein may contribute to a malignant phenotype of these tumours." (PMID 33167358, 2020). "In meningioma, overexpression of FBLN1 has previously been identified in the fibroblastic grade I histological subtype, characterised by a rich collagen matrix, when compared to the grade I meningothelial subtype." (PMID 33167358, 2020).
meningitis (1 paper, 2010). A disorder characterized by acute inflammation of the meninges of the brain and/or spinal cord. "On the basis of the 2D immunoblot data showing a different isoform pattern of Fibulin-1, we assumed a pathophysiological relevance of this protein in meningitis." (PMID 20386697, 2010).
metabolism (1 paper, 2025). "They found that Fibulin 1 levels were elevated inpatients with HF and impaired glucose metabolism." (PMID 40026492, 2025).
nutritional deficiency (1 paper, 2020). "Based on these results, Fibulin-1 silencing promotes apoptosis in our cell models, and Fibulin-1 overexpression may lead to cellular resistance to apoptosis induced by nutritional deficiency." (PMID 32612994, 2020).
osteoarthritis (1 paper, 2022). A noninflammatory degenerative joint disease occurring chiefly in older persons, characterized by degeneration of the articular cartilage, hypertrophy of bone at the margins and changes in the synovial membrane. "Of note, FBLN1, a marker of chondrocyte proliferation in osteoarthritis, is differentially expressed between oligoarticular FLS and ETB FLS." (PMID 36167601, 2022).
osteoporosis (1 paper, 2022). A condition of reduced bone mass, with decreased cortical thickness and a decrease in the number and size of the trabeculae of cancellous bone (but normal chemical composition), resulting in increased fracture incidence. "Furthermore, the generally acidic osteoporotic bone in untreated osteoporosis could support bone metastasis with the secretion of proteins such as COL1A1, COL4A2, NID1, FBLN1, and NRP2." (PMID 35159353, 2022).
pancreatic adenocarcinoma (1 paper, 2025). "FAP showed a similar effect on the prognosis of THCA and UVM as FBLN1, and was also associated with favorable prognosis of pancreatic adenocarcinoma (PAAD)." (PMID 40433364, 2025).
papillary thyroid cancer (1 paper, 2025). "Plasma fibulin-1 expression has been reported to be significantly lower in papillary thyroid cancer patients than in healthy individuals." (PMID 41301725, 2025).
primary brain tumour (1 paper, 2022). "CTSF and Fibulin-1 (FBLN1) levels were specifically upregulated in sera and tissues of patients with NSCLC BM compared with NSCLC without BM and primary brain tumour." (PMID 35217799, 2022).
sarcopenia (1 paper, 2025). Progressive decline in muscle mass due to aging which results in decreased functional capacity of muscles. "By hijacking Fbln1/FAK signaling, DAO not only rewires muscle energy metabolism but also erodes the mechanical infrastructure essential for force production—a dual assault that underscores its potential as a therapeutic target for sarcopenia and related myopathies." (PMID 41220805, 2025).
syndactyly (1 paper, 2022). A disease characterized by the presence of syndactyly, including syndromic and non-syndromic forms. "A missense mutation in fibulin-1 in a consanguineous family showed a novel syndrome of syndactyly and other abnormalities in the central nervous system (CNS), indicative of the crucial role of fibulin-1 in development of the CNS and various connective tissues." (PMID 36176297, 2022). "Since ARHGAP31 is one of the causative genes identified for AOS, and FBLN1 variation has been shown to cause syndactyly, we highly suspected the two variations together contributes to the TTLD phenotype in the proband." (PMID 36176297, 2022). "Since variation in FBLN1 has been shown to be associated with complex forms of syndactyly, the extra variation in FBLN1 gene was therefore suspicious to be the other candidate as a causative gene." (PMID 36176297, 2022).
thyroid-associated ophthalmopathy (1 paper, 2024). "It has been demonstrated that fibulin-1 is associated with thyroid-associated ophthalmopathy." (PMID 39200361, 2024).
uremia (1 paper, 2013). A clinical syndrome associated with the retention of renal waste products or uremic toxins in the blood. "Fibulin-1 levels correlated with markers of kidney function and uremia (P-creatinine, P-urea, and eGFR) with fibulin-1 levels increasing with deteriorating kidney function/increasing uremia." (PMID 23294625, 2013).